MAP1LC3A (microtubule associated protein 1 light chain 3 alpha)
Diseases named in the same sentence as MAP1LC3A in open-access papers (continued):
Sharing a sentence is not in itself a finding about the gene and the disease.
tumor (449 papers, 2004 to 2026). "High levels of MAP1LC3A have been observed in many tumor cell lines and are associated with impaired autophagic activity, which facilitates carcinogenesis." (PMID 35186475, 2022). "High values of N (2 and 3) were associated with low levels of expression of MAP1LC3A in tumor cells (p = 0.012, analysis of variance)." (PMID 30374741, 2018). "Patients whose tumour had high expression of MAP1LC3A, SNCA, and MAPT and low expression of CDK1, AP1S1, CASP3, TMPRSS6, and GSK3B inferred better overall survival than all other patients." (PMID 38642129, 2024). "Further Cox regression analysis showed that high expression of MAP1LC3A was related to poor survival, suggesting that dysregulation of mitophagy promoted the tumor progression." (PMID 35692054, 2022). "‘Stone-like’ MAP1LC3A is directly related to high grade tumors, aggressive tumor behavior and poor prognosis, and seems to reflect a severe type of autophagy during which autophagic debris accumulates." (PMID 28665306, 2017). "Previous studies have demonstrated that, in UM patients, there is a frequent overexpression of autophagy-related proteins, such as MAP1LC3A (microtubule-associated protein 1 light chain 3 alpha) and BECN1 (beclin 1), which are associated with tumor progression and poorer outcomes." (PMID 38920653, 2024). "Additionally, we observed that in tumor tissues, many highly expressed MRGs are associated with CNV gains, such as MTERFD1, SRC, and MAP1LC3A." (PMID 39512680, 2024). "Restoration of MAP1LC3A expression in ESCC cell lines led to inhibition of tumor growth in vivo." (PMID 37664173, 2023). "However, MAP1LC3A expression is positively correlated with high proliferative characteristics of tumor cells." (PMID 37664173, 2023). "According to genecards, the expression of MAP1LC3A was indeed suppressed in many tumor cell lines, suggesting that it may be involved in carcinogenesis." (PMID 35571123, 2022). "Compelling studies reported that the expression of MAP1LC3A was suppressed in many tumor cells including GBM, indicating that it might be involve in the tumorigenesis of various cancers." (PMID 35692054, 2022). "SERPINA1, MAP1LC3A, DIRAS3 were down-regulated in a high risk group and up-regulated in a low risk group, which were potentially tumor suppressor genes; HSPA8, HSPB8 were up-regulated in a high risk group and down-regulated in a low risk group, which were probably promoting oncogenes." (PMID 34876005, 2021). "In summary, NRG1, ITGA3 and MAP1LC3A may serve as tumor inducers by regulating autophagy and apoptosis in GBM." (PMID 31844032, 2019). "However, it is important to note that the immunohistochemical analysis of several tumor types reveals three types of MAP1LC3A expression: diffuse cytoplasmic, perinuclear, and ‘stone-like’ expression." (PMID 28665306, 2017). "This is consistent with our findings that low MAP1LC3A expression in ESCC may be related to the aggressiveness of malignant cells, whereas high MAP1LC3A expression increases the risk of poor prognosis and may be related to the proliferation of tumor cells." (PMID 37664173, 2023). "In both normal and tumor tissue, the highest levels of gene expression were observed for GABARAPL2, followed by MAP1LC3B and MAP1LC3A, the lowest for MAP1LC3C." (PMID 30374741, 2018). "Moreover, the mRNA expression levels of MAP1LC3A and FDX1 in PTC tissues were significantly lower than those in non-tumor thyroid tissues." (PMID 36333684, 2022). "Age was positively correlated with the fall in expression levels between healthy and tumor cells of the three following genes: ATG4B (Spearman’s correlation coefficient R = 0.352; p = 0.002), and MAP1LC3A (Spearman’s correlation coefficient R = 0.279; p = 0.017)." (PMID 30374741, 2018). "In addition, three genes, MAP1LC3A, PRRX1 and SYT11, were moderately downregulated in the tumor tissues." (PMID 25789025, 2015).
tumor (continued). "Three independent prognostic DEOSGs (PRODH, STK24, and MAP1LC3A) were identified by multivariate Cox proportional hazards regression analysis after consideration of confounding factors such as gender, tumor, node, and metastasis (TNM) stage, tumor (T) stage, and node (N) stage." (PMID 36180848, 2022).
cancer (304 papers, 2009 to 2026). A tumor composed of atypical neoplastic, often pleomorphic cells that invade other tissues. "Microtubule-associated protein 1 light chain 3-alpha (LC3A)-mediated autophagy conferred resistance to EGFR-TKIs in carcinoma cells." (PMID 36076996, 2022). "Microtubule associated protein 1 light chain 3 alpha (LC3A)-mediated autophagy in carcinoma cells confers resistance to EGFR-TKIs." (PMID 31527477, 2019). "Also, MAP1LC3A has been implicated in related diseases e.g. in cancers of the gastro intestinal system." (PMID 35105309, 2022). "We found that the NPS was negatively associated with LC3 (MAP1LC3A) expression in most cancers." (PMID 36170029, 2022). "We then explored the methylation levels (beta-values, HumanMethylation450) of MAP1LC3A, OPTN, PINK1, PRKN, SRC, BNIP3L, and BECN1 in pan-cancer and their association with gene expression and the immune cell infiltrates." (PMID 39859167, 2025). "MAP1LC3A was the only gene in the signature that exhibited hypermethylation, implying that this epigenetic process has some crucial role in cancer pathogenesis and immune cell infiltration." (PMID 39859167, 2025). "The analysis of CNVs in PRKN, OPTN, PINK1, SRC, BNIP3L, BECN1, and MAP1LC3A across various cancer types revealed significant heterogeneity in the types and frequencies of CNVs." (PMID 39859167, 2025). "In many human cancer cell lines, MAP1LC3A, a key molecule for mitophagy, is transcriptionally inactivated." (PMID 37664173, 2023). "WIPI2, ATG9B, MAP1LC3A, and RB1CC1 have higher frequencies of gain mutation frequencies in the pan-cancer analysis." (PMID 34636718, 2021). "Overall, these findings highlight the complex landscape of CNVs in PRKN, OPTN, PINK1, SRC, BECN1, BNIP3L, and MAP1LC3A across different cancer types, emphasizing the potential impact of these genetic alterations on cancer pathogenesis and the importance of considering CNVs in therapeutic strategies." (PMID 39859167, 2025). "Furthermore, we found hotspot mutations in the arginine-rich stretch in MAP1LC3A resulting in reduced cleavage of MAP1LC3A by ATG4B both in vitro and in vivo, suggesting a functional implication of this gene mutation in cancer development." (PMID 27256984, 2016). "Overall, the Spearman’s correlation coefficients varied across different cancer types, revealing distinct patterns of immune cell correlation with the expression of OPTN, PINK1, MAP1LC3A, PRKN, BNIP3L, BECN1, and SRC." (PMID 39859167, 2025). "Last, we gathered the IC50s of a wide variety of drugs among different cancer cell lines through the GDSC and CTRP databases and assessed the relationship between the mRNA values of MAP1LC3A, OPTN, SRC, BNIP3L, BECN1, PINK1, and PRKN and drug sensitivity." (PMID 39859167, 2025). "MAP1LC3A, AQP1, and AP1S1 were consistently amplified across cancer types whilst XAF1, CASP3, and SNCA exhibited copy deletions." (PMID 38642129, 2024). "Expression levels of the ferroptosis-related genes GCLC, MAP1LC3A, SLC7A11, and SLC39A8 in NAT10 KD cancer cells were significantly downregulated, therefore validating the results from our RNA-seq data." (PMID 37237981, 2023). "Consistent with previous reports, Pikfyve depletion led to accumulation of the lipidated form (LC3A/B-II) of MAP1LC3A/B protein (LC3A/B) and formation of vacuoles in vitro in the cancer cells." (PMID 38011559, 2023). "Our results showed significant downregulation in expression of essential genes related to ferroptosis, namely SLC7A11, GCLC, MAP1LC3A, and SLC39A8 in NAT10-depleted cancer cells." (PMID 37237981, 2023). "GSEA revealed that the DE-ATGs in the high ITGA3, MAP1LC3A, and NRG1 expression groups in the TCGA GBM cohort were mainly enriched in KEGG pathways related to autophagy and cancer." (PMID 31844032, 2019). "Notably, PRKN exhibited the highest alteration frequency, affecting 34% of all cancer samples, followed by OPTN (21%), PINK1 (18%), SRC (15%), BECN1 (13%), MAP1LC3A (9%), and BNIP3L (5%)." (PMID 39859167, 2025).
cancer (continued). "MAP1LC3A and SRC showed notable heterozygous amplifications in cancers like BRCA and LIHC." (PMID 39859167, 2025). "Here, we conduct a comprehensive analysis of a mitophagy-related gene signature, composed of PRKN, PINK1, MAP1LC3A, SRC, BNIP3L, BECN1, and OPTN, across various cancer types, revealing significant differential expression patterns associated with molecular subtypes, stages, and patient outcomes." (PMID 39859167, 2025). "In vivo, the mice in the model groups displayed cancer progression, and the expression of some of the autophagy-related genes, DRAM1, NBR1, ATG7, MAP1LC3A were also increased in mice given F. nucleatum or F. nucleatum with L-cysteine when compared to the untreated control mice." (PMID 37889013, 2023). "ATG5 and MAP1LC3A activate autophagy through the ATG5-ATG7-NCOA4 pathway, leading to ferritin degradation and thereby intracellular unstable iron accumulation, ultimately promoting ferroptosis in fibroblasts and cancer cells." (PMID 34284753, 2021). "Similarly, the modulation of the activity of MAP1LC3A (LC3) and OPTN could influence autophagosome formation and selective degradation of mitochondria, thereby affecting cancer cell survival." (PMID 39859167, 2025). "In addition, high mRNA levels of MAP1LC3A were shown to potentially activate the DNA damage response (12%) pathway, while potentially inhibit the activity of apoptosis (22%), the cell cycle (12%) and RTK (12%) pathways in pan-cancer." (PMID 39859167, 2025).
myopathy (8 papers, 2012 to 2025). A disease of the muscle in which the muscle fibers do not function properly. "Map1lc3a (autophagy-related ubiquitin-like modifier LC3 A) is involved in the formation of autophagosomes, and among Map1lc3a-related pathways are selective autophagy and mitophagy, alterations in both are known as important contributors to myopathy pathogenesis." (PMID 39948343, 2025).
gastrointestinal tumors (5 papers, 2013 to 2024). "Upregulation of MAP1LC3A was shown to correlate with an increase in Ki67 positive cells in gastrointestinal tumors." (PMID 28109268, 2017).
MAP1LC3A also shares sentences with these, for which no sentence is quoted: hepatocellular carcinoma (48 papers); neuroblastoma (38); gastric cancer (36); pancreatic cancer (36); colon carcinoma (33); prostate carcinoma (25); liver cancer (20); atherosclerosis (19); cervical carcinoma (19); neurodegenerative disease (19); non-small cell lung carcinoma (19); bacterial infection (18); Cerebral ischemia (18); esophageal cancer (17); ischemia (17); Sepsis (17); Stroke (17); adenovirus infection (16); leukemia (15); oral cancer (14); Alzheimer disease (13); bladder cancer (13); cardiac hypertrophy (13); liver fibrosis (13); renal fibrosis (13); colitis (9); Hyperglycemia (9); cholestasis (8); Cirrhosis (8); depression (8).
A further 356 diseases each share a sentence with MAP1LC3A in 8 papers or fewer.